FBLN2 (fibulin 2)
Diseases named in the same sentence as FBLN2 in open-access papers (continued):
Sharing a sentence is not in itself a finding about the gene and the disease.
tumor (46 papers, 2008 to 2025). "Collectively, these results demonstrated that VitA+ or VitA-Lrat+Fbln2+ aHSC was a unique tumor-associated aHSC subpopulation which likely produced 12-HHTrE by CYP1B1." (PMID 37156770, 2023). "Given that FBLN2 functions in the ECM, downregulation of FBLN2 can promote the migration and invasion of tumor cells thereby causing damage to the basement membrane." (PMID 35445008, 2022). "Association between perivascular fibulin-2 expression and elastosis, vessel invasion, basal-like tumours, triple negative tumours as well as detection mode (n = 272)." (PMID 33836007, 2021). "We found that high transcript expression of fibulin 2 (FBLN2) was significantly associated with advanced pathologic stage and tumor metastasis in UBUC, suggesting its role in cancer progression." (PMID 33194662, 2020). "In conclusion, we demonstrated that high FBLN2 immunoexpression is associated with aggressive tumor characteristics and independent prognostication of worse oncological outcomes in a large, well-characterized UC cohort." (PMID 33194662, 2020). "For instance, gelatinases MMP-2 and MMP-9 are highly associated with tumor progression and both can effectively cleave Fibulin-2." (PMID 28099917, 2017). "Despite the lack of somatic mutations, we found a significant association for two cases: the tumor suppressor FBLN2 and the cancer driver MYH11." (PMID 25578962, 2015). "Fibulin-2 deficiency impaired the ability of tumor cells to migrate and invade in Boyden chambers, to create a stiff extracellular matrix in mice, to cross-link secreted collagen, and to adhere to collagen." (PMID 23785517, 2013). "CIDE-A methylation was associated with ER positive tumours (P = 0.016), whilst FBLN2 methylation was associated with PR positive tumours (P = 0.013)." (PMID 20205715, 2010). "Furthermore, cases with high perivascular fibulin-2 were inversely associated with basal-like tumours and interval cancers (both p< 0.001)." (PMID 33836007, 2021). "Association between perivascular fibulin-2 expression and tumour subtypes (n = 272)." (PMID 33836007, 2021). "Here we show that reduced FBLN2 levels in normal mammary epithelial cells are associated with a significant reduction in integrin β1 (ITGβ1) and a discontinuous BM, and that FBLN2 expression is gradually lost in areas of tumour invasion." (PMID 30237579, 2018). "We examined whether fibulin-2 deficiency abrogated the ability of tumor cells to perform these functions." (PMID 23785517, 2013). "For example, FBLN2 is a tumor suppressor gene in NSCLC that inhibits tumor cell survival, proliferation, and invasion through multiple mechanisms, including the suppression of the MAPK/ERK and PI3K/AKT/mTOR signaling pathways." (PMID 41469472, 2025). "In CRC, loss of N‐Myc downstream‐regulated gene 4 (Ndrg4) function in organoid models triggered neuronal secretion of tumor-promoting factors, including nidogen 1 and fibulin 2, identifying novel therapeutic targets within neurogenic signaling pathways." (PMID 41163091, 2025). "Further investigations are required to disseminate the functional expression of FBLN2 in each subtype, and the epithelial versus stromal expression of FBLN2 in tumor microenvironment." (PMID 39110274, 2024). "This agrees with the notion that FBLN2 can potentially have a dual role as a cancer promotor or inhibitor based on tumor status." (PMID 39110274, 2024). "According to tumor grade, Fbln2 expression was significantly decreased in grade 3 compared to grade 1 (P < 0.01) and grade 2 (P < 0.05)." (PMID 39110274, 2024). "Patients with higher tumor proliferation ER + Her2- showed a significant downregulation of Fbln2 compared to Lower proliferation group (P < 0.0001)." (PMID 39110274, 2024). "In concordance with the results of in vitro experiments, in vivo assessment indicated that downregulation of FBLN2 inhibited tumor growth in the mice model, which further verified the oncogenic role of FBLN2 in HCC." (PMID 37162505, 2023).
tumor (continued). "Higher expression of FBLN2 was observed in HCC tumor tissues (H-score: 266.76 ± 28.41) than the liver tissues present adjacent to the tumors (H-score: 227.37 ± 41.69) (P < .05)." (PMID 37162505, 2023). "In recent times, several studies provided accumulating evidence for tumor-related properties of FBLN2 in various tumor types." (PMID 37162505, 2023). "In particular, FBLN2, one of the hub genes, is an independent protective factor in HCC patients and is associated with tumor immunity." (PMID 36768989, 2023). "Subcutaneous xenograft mouse models showed the tumor growth pattern after fibulin-2 silence in vivo." (PMID 37162505, 2023). "Basement membrane destabilization associated with the loss of FBLN2 contributes to increased cancer cell migration and invasion, and high expression of CSF1 and macrophage infiltration are associated with the tumor, node and metastasis (TNM) stage of CRC." (PMID 36845686, 2023). "Experiments in vivo showed that FBLN2 knockdown in the subcutaneous tumor resulted in an obvious reduction in tumor volume." (PMID 37162505, 2023). "In contrast, another study found that FBLN2 promoted tumor growth by interacting with activated β integrin receptor in CRC." (PMID 35445008, 2022). "At the protein level, high FBLN2 expression was associated with a poor prognosis (p < 0.001), and FBLN2 expression was significantly higher in tumor samples than in normal samples (p < 0.001)." (PMID 35445008, 2022). "In conclusion, this population-based study indicates a strong relation between reduced perivascular fibulin-2 content and vascular invasion as well as tumour detection during screening intervals." (PMID 33836007, 2021). "Multivariate analysis of RFS was performed for all cases by including perivascular fibulin-2 expression along with basic histopathologic markers such as tumour diameter, histologic grade and lymph node status." (PMID 33836007, 2021). "Abnormal expression of FBLN2, one of the fibulin family members, contributes to tumor initiation and development." (PMID 34769264, 2021). "Taken together, our data indicate that FBLN2 is methylated and exerts a tumor suppressor function through modulation of MAPK/ERK and AKT pathways and regulation of cell adhesion and ECM genes." (PMID 34769264, 2021). "All of these findings suggest that fibulin-2 promotes and inhibits tumor progression, depending on the cell types, degree of malignancy, and stage of cancer." (PMID 34063320, 2021). "In contrast, fibulin-2 favors the malignant progression of lung adenocarcinoma by enhancing the attachment of tumor cells to collagen and collagen cross-linking." (PMID 34063320, 2021). "In primary lung tumor tissues, DNA methylation of FBLN2 was detected in 81.1% (30/37) of tumor tissues." (PMID 34769264, 2021). "And the combination of WCF with DDP significantly inhibited tumor growth, increased organelle vacuolations and decreased colocalization of Integrin β1 and its ligands including fibulin-2 and laminin." (PMID 33041787, 2020). "Pearson’s test showed a negative significant correlation (P < 0.001) between the level of FBLN2 expression and tumour grade." (PMID 30237579, 2018). "The FBLN2 expression pattern in the normal adult human breast around tumour tissue differs strongly from that in the adult mouse where FBLN2 was only detected at times of BM remodelling during very early pregnancy." (PMID 30237579, 2018). "In human nasopharyngeal carcinoma, fibulin-2 is indicated to assume tumor-suppressive effects by inhibiting cell growth and proliferation, cell migration and invasion, and angiogenesis by downregulating pro-angiogenesis factors." (PMID 30227601, 2018). "In contrast, fibulin-2 is shown to enhance malignant progression of metastatic lung adenocarcinoma by promoting cross-linking of secreted collagen molecules and tumor cell adherence." (PMID 30227601, 2018). "In IDC I–II samples, Fibulin-2 was barely detected in tumor cell masses and ADAMTS-5 was present in masses of epithelial cells." (PMID 28099917, 2017).
tumor (continued). "We have also explored the consequences of Fibulin-2 degradation within the tumor extracellular matrix." (PMID 28099917, 2017). "In this regard, Fibulin-2 can display both tumor-promoting and tumor-protective properties in different types of neoplasia." (PMID 28099917, 2017). "FBLN2 has been proposed before to be a tumor suppressor with a cancer-related function that seems to be specific of the protein produced in tumor cells." (PMID 25578962, 2015). "FBLN2, BIN1, FN1 and TNC examples suggest that the variants that are altered in the same direction in several cancer types have significant roles in tumor initiation and progression." (PMID 25908786, 2015). "As tumor suppressor genes, fibulin-2 and fibulin-5 were widely considered to be associated with the suppression of tumor growth, invasion, and angiogenesis." (PMID 25885889, 2015). "Here we showed that fibulin-2 promotes cross-linking of secreted collagen molecules and tumor cell adherence to collagen, biochemical functions that are presumably unrelated to its structural role as a bridge between matrix molecules." (PMID 23785517, 2013). "Loss-of-function experiments in tumor cells revealed that fibulin-2 was required for tumor cells to grow and metastasize in syngeneic mice, a surprising finding given that other intra-tumoral cell types are known to secrete fibulin-2." (PMID 23785517, 2013). "As a tumor suppressor gene, Fibulin-2 inhibited tumor growth, invasion and angiogenesis in hepatocellular carcinoma and breast cancer." (PMID 24236050, 2013). "Here we posited that fibulin-2, a matrix glycoprotein that functions biomechanically as an inter-molecular clasp, stabilizes tumor extracellular matrix and thereby drives malignant progression." (PMID 23785517, 2013). "Collectively, these findings suggest that tumor cells required fibulin-2 for the creation of a stiff extracellular matrix and adherence to collagen." (PMID 23785517, 2013). "Among downregulated genes, some have tumor suppressive activities, e.g., FBLN2, LYPD1, SVEP1." (PMID 41469472, 2025). "We, therefore, hypothesized that this preferential correlation can affect FBLN2 expression in molecular subtypes, particularly with the heterogeneous composition of tumor microenvironment." (PMID 39110274, 2024). "A tumor suppressor role for fibulin-2 has also been observed in gastric cancer." (PMID 38396702, 2024). "Furthermore, FBLN2, one of the hub genes, is an independent protective factor in HCC patients and is associated with tumor immunity." (PMID 36768989, 2023). "On the one hand, murine tumor cells cannot fully mimic human tumor cells, and on the other hand, even in human cancer, FBLN2 may play a dual role, dependent on cell type and context." (PMID 34769264, 2021). "This could reflect different protein requirements at the various progression stages, where FBLN2 presence may suppress tumour invasion in the early stages but may enable cancer cells to survive and form metastases once invasion has occurred." (PMID 34565423, 2021). "FBLN2 knockdown led to significantly increased tumor cell migration and invasion abilities." (PMID 34769264, 2021). "Taken together, based on our data, FBLN2 is a tumor suppressor in NSCLC." (PMID 34769264, 2021). "Trends were also present for associations between perivascular fibulin-2 expression and small tumour size (< 2 cm) (p = 0.056), as well as negative nodal status (p = 0.068)." (PMID 33836007, 2021). "Hypothetically, low elastosis content, and therefore a low fibulin-2 content, may facilitate tumour cell migration and invasion." (PMID 33836007, 2021). "To speculate, a reduced anchoring of fibulin-2 could destabilize basement membranes and enhance the ability of tumour cells to migrate and invade through the ECM." (PMID 33836007, 2021). "Depending on the tissue context, FBLN2 may act as either a tumor promoter or a tumor suppressor in different cancer models." (PMID 33194662, 2020).
tumor (continued). "Our observations of tumor slices revealed that Integrin β1 and its ligands, such as fibulin-2 and laminin staining could be clearly viewed in all the groups." (PMID 33041787, 2020). "FBLN2 re-expression also inhibited tumor growth and angiogenesis in vivo." (PMID 33194662, 2020). "Collectively, these studies show the importance of fibulin-2 in tumor development." (PMID 31508361, 2019). "However, entire Fibulin-2 was mainly detected in normal tissues and an approximately 50 kDa immunoreactive band was also discernible in different tumor but also in normal samples." (PMID 28099917, 2017). "In IDC II and IDC II–III, Fibulin-2 was in the periductal and perivascular stroma or in some well delimited cells of the tumor cells masses; whereas ADAMTS-5 showed a faint immunoreactivity paralleled to that of Fibulin-2 or diffusely presented in masses of epithelial cells." (PMID 28099917, 2017). "Taking into account these results, it could be hypothesized that ADAMTS-12 protects Fibulin-2 from the degradation mediated by ADAMTS-5, which could influence the equilibrium between tumor-promoting and tumor-preventing functions attributed to Fibulin-2." (PMID 28099917, 2017). "Our data strongly suggest that the cleavage by aggrecanases, but especially by ADAMTS-5, could influence the balance between pro- and anti-tumor effects elicited by Fibulin-2." (PMID 28099917, 2017). "Our new data support that the protection that ADAMTS-12 exerts on Fibulin-2 degradation by aggrecanases might form part of a defensive response against tumor invasion by strengthening the physical barrier created by Fibulin-2 and its interacting partners." (PMID 28099917, 2017). "We also wanted to evaluate whether a potential degradation of Fibulin-2 by ADAMTS-5 could promote other changes in the tumor microenvironment." (PMID 28099917, 2017). "Gelatinases MMP-2 and MMP-9 are responsible for Fibulin-2 degradation in these tumor cells." (PMID 28099917, 2017). "In consequence, pro or anti-tumor activities of ADAMTS-12 could also be influenced by factors other than interaction with fibulin-2." (PMID 24457941, 2014). "Most studies on the role of fibulin-2 in cancer have shown that it functions as a tumor suppressor." (PMID 23785517, 2013). "Fibulin-2 was detected in elastic tissues within bronchi and vascular structures in adjacent normal lung, in a “fibrillar” pattern between tumor cells and surrounding tumor acini, and in a “fibrotic” pattern within intra-tumoral fibrotic bands." (PMID 23785517, 2013). "However, when Luminal A and Luminal B (HER2-negative) tumours were combined in one group and analyzed, low perivascular fibulin-2 was associated with reduced RFS (p = 0.001), but not DSS (p = 0.14)." (PMID 33836007, 2021). "In future studies, it could therefore be important to examine Fbln2′s role in the survival of tumour cells under conditions experienced during metastasis, as well as FBLN2 expression in both the metastasis itself and in the matched primary tumour." (PMID 30237579, 2018). "Thus, it can be hypothesized that cleavage of Fibulin-2 by ADAMTS-5 could form part of the strategies employed by tumor cells to degrade ECM components thereby facilitating tumor cell invasion." (PMID 28099917, 2017). "Thus, it can be speculated that exogenous ADAMTS-12 may interact with fibulin-2 produced by A549 cells and thereby inducing the anti-tumor effect observed." (PMID 24457941, 2014). "However, a growing number of studies point out the anti-tumor properties of fibulin-2." (PMID 24457941, 2014). "In KP cells, fibulin-2 western blotting revealed two bands, but analysis of Fbln2 transcripts revealed only the spliced form, and depletion of fibulin-2 abrogated tumor growth and metastasis, which stands in contrast to tumor suppressor effects of fibulin-2 reported previously." (PMID 23785517, 2013).
tumor (continued). "Thus, fibulin-2 enhanced tumor cell proliferation, migration, and invasion, which could have mediated its promotion of tumorigenesis and metastasis." (PMID 23785517, 2013). "Other few proteins such as Fibulin-2, EMILIN-2, and Decorin, are described also to have tumor suppressive functions." (PMID 34299025, 2021). "We found that collagen, biglycan, fibulin 2, and FSTL1 can induce tumor cell invasion under the bead, though only collagen seemed to allow cells to migrate through the bead." (PMID 29615735, 2018). "Five genes (62.5%) demonstrated tumour acquired methylation (EMILIN2, SALL1, DBC1, FBLN2 and CIDE-A), whilst the remaining 3 (COMP, EPSTI1, SIM2) showed equal methylation in the corresponding normal breast tissue DNA." (PMID 20205715, 2010). "The limitation of this study is the utilization of Fbln2 mRNA data, and not protein data, from publicly available datasets that represent whole tissue transcriptome with no dissection of tumor versus microenvironment expression." (PMID 39110274, 2024). "These in vivo findings agree perfectly with the tumor suppression role already suggested for both proteins separately, although the urethane model did not suggest a protective role for fibulin-2." (PMID 38396702, 2024). "In contrast, Basal and Her2 showed a higher expression compared to LumB, but not Lum A, which suggests an increased expression of Fbln2 in tumor cells, particularly with EMT, myoepithelial turnover, and tumor invasion." (PMID 39110274, 2024). "In the absence of ADAMTS14, fibulin 2 levels are increased, and fibulin 2 in turn outcompetes latent TGFβ for binding to Fibrillin, facilitating the release of active TGFβ into the tumour milieu." (PMID 37929635, 2024). "Multivariate analysis was also done for the same basic histopathologic factors in addition to perivascular fibulin-2 expression within the group of luminal (HER-2 negative) tumours." (PMID 33836007, 2021). "High perivascular fibulin-2 was inversely associated with BVI and LVI (both p<0.001) as compared to tumours without BVI or LVI." (PMID 33836007, 2021). "In contrast, significant levels of GAGs were detected in the stroma surrounding tumour tissue within all tested sections with the less intact network of fibrous collagen, and where FBLN2 expression was absent." (PMID 30237579, 2018). "Moreover, some tumor regions close to large blood vessels were encircled by ADAMTS-5 and Fibulin-2 positive cells." (PMID 28099917, 2017). "The FBLN2 gene is silenced through methylation or deletion in various tumor types, and reintroduction of fibulin-2 into cancer cells that do not express fibulin-2 reduces motility and invasion in vitro." (PMID 23785517, 2013). "The mCAF subset of the tumor stroma specifically expressed transcripts of a large variety of ECM-related genes, such as glycoproteins (Dcn, Lum, and Vcan), structural proteins (Col14a1), matricellular proteins (Fbln1, Fbln2, and Smoc), and matrix-modifying enzymes (Lox and Loxl1)." (PMID 30514914, 2018). "However, it cannot be ruled out that other enzymes also contribute to degrade Fibulin-2 in tumor processes." (PMID 28099917, 2017). "However, studies involving the relationship between fibulin-2 and tumor immunity are lacking." (PMID 36768989, 2023). "Additionally, we also found that ADAMTS-12 may elicit pro-tumor effects in the absence of fibulin-2." (PMID 24457941, 2014). "Thus, malignant progression was dependent specifically upon tumor cell-derived fibulin-2, which could not be offset by other cellular sources of fibulin-2." (PMID 23785517, 2013). "However, tumor cells grew and metastasized equally well in Fbln2-null and -wild-type littermates, implying that malignant progression was dependent specifically upon tumor cell-derived fibulin-2, which could not be offset by other cellular sources of fibulin-2." (PMID 23785517, 2013).